CACNA1C (calcium voltage-gated channel subunit alpha1 C)
Diseases named in the same sentence as CACNA1C in open-access papers (continued):
Sharing a sentence is not in itself a finding about the gene and the disease.
Constipation (1 paper, 2025). Infrequent or difficult evacuation of feces. "Moreover, the transcription of CACNA1C in the Urd-treated C3 KO model was higher than in the Lop-induced constipation model, while, after treatment with AELP, the transcription of CACNA1C was greater in the Lop-induced constipation model than in the C3 KO model." (PMID 41011160, 2025).
Crohn disease (1 paper, 2014). A gastrointestinal disorder characterized by chronic inflammation involving all layers of the intestinal wall, noncaseating granulomas affecting the intestinal wall and regional lymph nodes, and transmural fibrosis. "Interestingly, CACNA1C has reported to be enriched in pathway analysis of inflammatory conditions such as Crohn's disease." (PMID 24763700, 2014).
dental caries (1 paper, 2014). The decay of a tooth, in which it becomes softened, discolored, and/or porous. "Whether p.G1911R in CACNA1C contributed to any of the other phenotypes displayed by the proband and previously associated with CACNA1C mutations in TS (e.g., facial dysmorphia and dental caries) is not known at this time." (PMID 25184293, 2014).
diffuse large B-cell lymphoma (1 paper, 2022). "Further, loss of expression of the CACNA1C gene results in rituximab resistance in diffuse large B-cell lymphoma 29-31." (PMID 36168622, 2022).
familial hyperinsulinism (1 paper, 2022). An instance of hyperinsulinism (disease) that is caused by an inherited modification of the individual's genome. "Next-generation sequencing (NGS) of 219 genes associated with familial hyperinsulinism or related disorders of glucose metabolism (e.g., monogenic diabetes, disorders of glycogen/fatty acid/ketone metabolism) revealed one candidate gene variant in CACNA1C." (PMID 35897673, 2022).
Fowler syndrome (1 paper, 2022). "In a few cases, the systems disagree like in case 6, where the clinical picture is not likely to be caused by a de novo CACNA1C C-terminal tail variant, and in case 9, where the clinical diagnosis is Fowler syndrome, a quite unique recessive clinical condition." (PMID 33981013, 2022).
gastric adenocarcinoma (1 paper, 2021). "CACNA1C overexpression has already been described in colorectal or gastric adenocarcinomas, with CACNA1C appearing in the top 10% of the most augmented genes." (PMID 34563241, 2021).
Hyperhidrosis (1 paper, 2023). Abnormal excessive perspiration (sweating) despite the lack of appropriate stimuli like hot and humid weather. "PAI1 inhibition with PAI-039 or Pai1 deficiency could induce up-regulated CHRNA1, ACH, AQP5, and CACNA1C expression and sweat secretion in hydrochloride-induced hyperhidrosis mice." (PMID 37542348, 2023). "Pai1-Tg mice demonstrated down-regulated secretion of ACH in the serum and down-regulated mRNA and protein levels of AQP5 (and 6 F) and CACNA1C in sweat glands of hydrochloride-induced hyperhidrosis when compared with normal mice exposure to hydrochloride." (PMID 37542348, 2023). "PAI1 inhibits CHRNA1-mediated hydrochloride-induced hyperhidrosis, with decreased sweat gland secretion and diminished ACH, AQP5, and CACNA1C expression." (PMID 37542348, 2023). "PAI1 regulation could alter the relative expression of CACNA1C and AQP5, which are vital components involved in the process of sweat secretion and pathological hyperhidrosis." (PMID 37542348, 2023).
hypospadias (1 paper, 2022). Hypospadias is the displacement of the urethral meatus on the ventrum of the penis. "This was associated with increased mRNA expression of Ca2+ channels important in regulating VSMC Ca2+ influx, specifically CACNA1C (P = 0.03), IP3R (P = 0.007), TRPM2 (P = 0.001), SERCA (P = 0.008), and RyR1 (P = 0.01) in boys with hypospadias vs. controls." (PMID 35567552, 2022).
ischemic stroke (1 paper, 2024). A stroke disorder caused by obstruction of blood flow to the brain, due to thrombotic (local blood clot formation) or embolic (due to a blood clot or other material traveling from another site) event. "Interestingly, CACNA1C (rs10848683 variant) is also associated with ischemic stroke." (PMID 39228919, 2024).
keratoconus (1 paper, 2025). A degenerative, structural disorder of the eye, characterized by a cone-shaped protrusion of the cornea. "In the corneal samples of patients with keratoconus, calcium voltage-gated channels including CACNA1C, CACNA1G, CACNA2D1, and CACNA2D4 were found to be down-regulated that could be indicative of reduced cell proliferation as observed in keratoconus." (PMID 39420106, 2025). "As a consequence, down-regulated voltage-gated calcium channels in CACNA1C, CACNA1G, CACNA1D1, and CACNA2D4, and purinergic receptors P2RX1 along with the down- regulated transcription factors including JUN and MYC can be attributed to reduced cell proliferation in keratoconus." (PMID 39420106, 2025).
metastatic disease (1 paper, 2019). "The observed overexpression of CACNA1A, CACNA1C, and CACNA1D suggests that they are likely targets for cancer treatment, as blockage or partial inhibition of their expression could help to modulate the progression of metastatic disease." (PMID 31416476, 2019).
myocarditis (1 paper, 2024). Myocarditis is a condition that is characterized by inflammation of the heart muscle (myocardium). "According to the ceRNA mechanism, NONHSAT122636.2 and CACNA1C are downregulated, while miR-2110 is upregulated in patients with myocarditis." (PMID 39150929, 2024).
Noonan syndrome with multiple lentigines (1 paper, 2023). A rare multisystem genetic disorder characterized by lentigines, hypertrophic cardiomyopathy, short stature, pectus deformity, and dysmorphic facial features. "This is also the case for 8/14 syndromic HCM (CACNA1C, FLNC, PRKAG2, PTPN11 (Noonan), PTPN11 (Noonan syndrome with multiple lentigines), RAF1, RIT1, TTR), 3/12 DCM (DES, TNNC1 and TNNT2), and 2/6 ARVC (JUP, TMEM43) gene-disease pairs." (PMID 37872640, 2023).
pancreatic cancer (1 paper, 2009). "We confirmed that CACNA1C was amplified in HSC45 cells, but not in the other gastric, colon, or pancreatic cancer cell lines using genomic qPCR analysis (data not shown)." (PMID 19545448, 2009).
Psychotic episodes (1 paper, 2024). Periods of time during which an individual experiences significant disturbances in their thoughts, perceptions, emotions, and behavior, resulting in a loss of touch with reality. "Again, previous research has established the CACNA1C-rs1006737 A allele as a risk factor for SZ through GWAS and meta-analytic approaches and has demonstrated its detrimental effect on longitudinal GAF scores and recovery after psychotic episodes." (PMID 38720004, 2024).
sick sinus syndrome (1 paper, 2021). A constellation of signs and symptoms which may include syncope, fatigue, dizziness, and alternating periods of bradycardia and atrial tachycardia, which is caused by sinoatrial node dysfunction. "In this report, we further expand the cardiac phenotype of CACNA1C pathogenic variants to include AF and sick sinus syndrome." (PMID 33797204, 2021). "Through this four‐generation pedigree, we have expanded the phenotype of CACNA1C disorders to include AF and sick sinus syndrome." (PMID 33797204, 2021).
stress-related disorder (1 paper, 2018). Stress-related disorders are mental health disorders that are a result of an atypical response to both short and long-term anxiety due to physical, mental, or emotional stress. "The fact that CACNA1C is also able to interact with the environment during adulthood, by modulating stress susceptibility, could explain its linkage to stress-related disorder such as MDD and BPD." (PMID 28696432, 2018).
sudden cardiac death (1 paper, 2017). "Among these genetic anomalies, only four variants, i.e., KCNQ1, KCNE1, SCN1A, and CACNA1C, were previously associated with SUDEP or other disorders associated with sudden cardiac death (SCD)." (PMID 29261713, 2017).
temporal lobe epilepsy (1 paper, 2025). A localization-related (focal) form of epilepsy characterized by recurrent seizures that arise from foci within the temporal lobe, most commonly from its mesial aspect. "This study aims to expand the phenotype associated with CACNA1C variants and utilize bioinformatics tools to explore whether CACNA1C is the pathogenic gene of familial temporal lobe epilepsy." (PMID 41177904, 2025). "A recent study found that abnormal expression of the α1c subunit in the hippocampal tissue of patients with temporal lobe epilepsy (TLE) suggests that CACNA1C may be involved in the pathogenesis of TLE." (PMID 41177904, 2025).
vascular dementia (1 paper, 2024). A degenerative vascular disorder affecting the brain. "Similarly, CACNA1C (rs11062164 variant) was significantly associated with vascular dementia." (PMID 39228919, 2024).
ventricular extrasystoles (1 paper, 2022). "The CACNA1C agonist ibutilide unsurprisingly is associated with cardiac adverse effects like ventricular extrasystoles in approximately 5% of individuals, as well as tachycardia." (PMID 36055211, 2022).
psychiatric disorder (94 papers, 2013 to 2026). A disorder characterized by behavioral and/or psychological abnormalities, often accompanied by physical symptoms. "The cross-disorder risk gene CACNA1C encoding the α1 subunit of the L-type calcium channel Cav1.2 has repeatedly been associated with various psychiatric disorders." (PMID 42009796, 2026). "CACNA1C is linked to risk for psychiatric disorders where anhedonia is a symptom, thus we examined hedonic reactions to sucrose in a rat model of low‐dose Cacna1c." (PMID 40263772, 2025). "This study sought to directly investigate how variation in Cacna1c dosage impacts the HPA axis using a heterozygous Cacna1c rat model that reflects the reduced hippocampal CACNA1C expression associated with psychiatric disease." (PMID 40565009, 2025). "Genome-Wide Association Studies (GWAS) have identified Cacna1C as a high-risk gene for psychiatric disorders." (PMID 39268349, 2024). "A genomic study further revealed that single nucleotide polymorphisms (SNPs) in CACNA1C, identified as a cross-disorder risk gene, are linked to the prognosis of psychiatric disorders, echoing the results of our investigation." (PMID 39184138, 2024). "The role of the L-type Ca2+ channel-encoding gene Cacna1C in psychiatric disorders also exhibits variability." (PMID 39268349, 2024). "Large-scale GWASs have identified CACNA1C as a risk gene for multiple psychiatric disorders, including schizophrenia." (PMID 38491019, 2024). "Most studies suggest that Cacna1C is a highly risk-associated gene for psychiatric disorders, with its overexpression leading to emotional, cognitive, and memory deficits." (PMID 39268349, 2024). "Gene expression analysis in post-mortem brain tissue or fibroblast-derived neurons of risk allele carriers revealed altered CACNA1C mRNA expression levels, further supporting its implication in the pathology of psychiatric disorders." (PMID 39370418, 2024). "Patients with genetic variations in the CACNA1C gene have been shown to have increased risk for psychiatric disorders." (PMID 37422671, 2023). "For example, crossing B6 males with deletion of Cacna1c and Tcf7l2 genes associated with multiple psychiatric diseases with wild-type females from 30 inbred laboratory strains resulted in highly variable, sometimes opposing, effects." (PMID 35813596, 2022). "For instance, several large-scale genome-wide association studies (GWASs) identified CACNA1C as a critical candidate susceptibility gene in multiple psychiatric disorders, including SCZ, autism, bipolar disorder (BD), and major depression." (PMID 35220405, 2022). "A series of GWAS and WES studies have suggested causal links between common and rare variants of CACNA1C and psychiatric disorders including SCZ, BD, and ASD." (PMID 35220405, 2022). "Another SNP in the CACNA1C encoding gene, rs10848683C/T, confers a higher risk of developing psychiatric disorders, including BD and SCZ, in subjects with family backgrounds." (PMID 36193501, 2022). "Large-scale genome-wide association studies have consistently shown that genetic variation in CACNA1C, a gene that encodes calcium voltage-gated channel subunit alpha1C, increases risk for psychiatric disorders, including PTSD." (PMID 34282125, 2021). "This association is further supported by functional magnetic resonance imaging studies that have correlated the presence of the risk-associated CACNA1C SNP (rs1006737) and activation of brain circuitries that are characteristic of patients with mental illness." (PMID 33375447, 2020). "CACNA1C, a common risk gene for five major psychiatric disorders, has been associated with spatial working memory in BIP60." (PMID 32518222, 2020). "CACNB2, together with CACNA1C, is one of most consistently found risk genes for psychiatric disorders, particularly SCZ and BD." (PMID 31331039, 2019). "Several SNPs in CACNA1C have been linked to psychiatric disorders with most of them being located in a large intron (~330 kb) between exons 3 and 4 (intron 3)." (PMID 31331039, 2019).
psychiatric disorder (continued). "We report that healthy human subjects bearing alleles in the CACNA1C gene associated with risk for psychiatric disorders show poorer reversal performance on a probabilistic RL task than non-risk allele carriers." (PMID 30304534, 2019). "In a parallel gene × environment design in humans, we additionally demonstrate that SNPs in CACNA1C significantly interact with adverse life events to alter the risk to develop symptoms of psychiatric disorders." (PMID 28696432, 2018). "In this study we aimed to investigate how CACNA1C modulates the risk to psychiatric disorders in dependence of environmental, developmental and circuit specific factors, using both genetic mouse models and human data." (PMID 28696432, 2018). "The CACNA1C calcium-channel-regulating gene has repeatedly emerged in association with severe psychiatric disorders, but the mechanisms through which it affects disorder risk are poorly understood." (PMID 29471866, 2018). "The CACNA1C gene has also been implicated in the pathophysiology of psychiatric disease, rendering it an important target for understanding learning mechanisms not only in normal but also psychiatric conditions." (PMID 28604818, 2017). "Calcium influx through high-voltage-gated Ca2+ channels is central to synaptic plasticity, and altered expression of Cav1.2 channels and the CACNA1C gene have been associated with severe learning deficits and psychiatric disorders." (PMID 28604818, 2017). "In our study we observed that some of the CACNA1C variants for psychiatric disorders were found to be associated with sleep latency in babies at 8 months-of-age." (PMID 28792954, 2017). "CACNA1C variants for psychiatric disorders were found to be associated with long sleep latency among 8-month-old infants." (PMID 28792954, 2017). "Seven variants that were earlier associated (genome-wide significantly) with psychiatric disorders at CACNA1C were selected for analyses." (PMID 28792954, 2017). "Until now, genome-wide association studies have detected seven variants at CACNA1C which are associated with psychiatric disorders." (PMID 28792954, 2017). "Calcium channel subunits, including CACNA1C, have been associated with multiple psychiatric disorders." (PMID 27276213, 2016). "The SNP rs1006737 is located in intron 3 of CACNA1C, along with two other SNPs associated with psychiatric disease." (PMID 27276213, 2016). "It has been reported that genes encoding VGCC subunits, especially CACNA1C, are associated with psychiatric disorders." (PMID 26136667, 2015). "Smaller sample studies of healthy and psychiatric disorder populations have found that the CACNA1C risk allele increases mRNA transcript and alters Akt pathway activation." (PMID 24944871, 2014). "Specifically, CACNA1C, a voltage-gated calcium channel involved in neuronal signaling and shown to increase risk of psychiatric disorders, was shared across multiple hormone-related pathways, suggesting a broader role of calcium signaling in neuronal and endocrine regulation." (PMID 40253403, 2025). "Such altered associative learning may contribute to the association between genetic variation in Cacna1c and psychiatric disorders." (PMID 31910256, 2020). "Similar results were observed for CACNA1C in the present study, although several other independent studies reported the involvement and the association of the specific SNP rs1006737 in CACNA1C with psychiatric disorders in European, Danish, and Spanish populations." (PMID 33076578, 2020). "CACNA1C codes for the α1C subunit of the Cav1.2 channel is involved in the proper functioning of the hippocampus, amygdala, and mesolimbic reward system circuits, which are strongly implicated in the pathophysiology of psychiatric disorders." (PMID 32411272, 2020).